MED30 (mediator complex subunit 30)
Description:
Component of the Mediator complex, a coactivator involved in the regulated transcription of nearly all RNA polymerase II-dependent genes. Mediator functions as a bridge to convey information from gene-specific regulatory proteins to the basal RNA polymerase II transcription machinery. Mediator is recruited to promoters by direct interactions with regulatory proteins and serves as a scaffold for the assembly of a functional preinitiation complex with RNA polymerase II and the general transcription factors.
Synonyms: Trap25; THRAP6; MED30S
Tractability: Small molecule: a structure with a bound ligand is known. PROTAC: ubiquitination databases record sites on it; its protein half-life has been measured.
Gene: Protein-coding gene on chromosome 8 (117,520,710 to 117,540,262, forward strand). Ensembl gene ENSG00000164758.
Subcellular location: Nucleus
Subcellular location (Human Protein Atlas): Nucleoplasm
Pathways (Reactome):
Gene expression (Transcription): Generic Transcription Pathway; MLL4 and MLL3 complexes regulate expression of PPARG target genes in adipogenesis and hepatic steatosis
Developmental Biology: Transcriptional regulation of white adipocyte differentiation
Disease: RSV-host interactions
Metabolism: PPARA activates gene expression
Gene Ontology:
Molecular function: nuclear thyroid hormone receptor binding; protein binding; transcription coactivator activity; transcription coregulator activity; nuclear vitamin D receptor binding; ubiquitin protein ligase activity
Biological process: positive regulation of DNA-templated transcription; positive regulation of transcription initiation by RNA polymerase II; positive regulation of transcription elongation by RNA polymerase II; RNA polymerase II preinitiation complex assembly; protein ubiquitination
Cellular component: core mediator complex; mediator complex; nucleus; nucleoplasm; ubiquitin ligase complex
Genetic constraint (gnomAD): Loss-of-function variants: 4 observed, 10.81 expected, observed/expected ratio (o/e) 0.37, 90% interval 0.18 to 0.85. The upper end of that interval is the gene's LOEUF score, 0.85, which puts it in group 3 of 6, group 1 being the genes least tolerant of losing a copy. Missense variants: 157 observed, 177.62 expected, observed/expected ratio (o/e) 0.88, 90% interval 0.77 to 1.01. Synonymous variants: 64 observed, 74.89 expected, observed/expected ratio (o/e) 0.85, 90% interval 0.7 to 1.05.
Homologues: Orthologues: chimpanzee MED30 (100% identical), macaque MED30 (100% identical), pig MED30 (98% identical), rabbit MED30 (98% identical), dog MED30 (97% identical), guinea pig MED30 (97% identical), rat Med30 (96% identical), mouse Med30 (95% identical), tropical clawed frog med30 (83% identical), zebrafish med30 (77% identical), Drosophila melanogaster MED30 (39% identical).
Diseases named in the same sentence as MED30 in open-access papers:
MED30 is named in the same sentence as 21 diseases in open-access papers, as found by Europe PMC text mining. Sharing a sentence is not in itself a finding about the gene and the disease. The quoted sentences say what the papers report.
breast carcinoma (3 papers, 2007 to 2022). "MED30 has also been reported to be overexpressed in various breast cancer cell lines, along with MED1 and MED24." (PMID 35205681, 2022). "Recent reports have demonstrated that the number of MED30 copies is also amplified in breast cancer." (PMID 21853135, 2011).
gastric cancer (3 papers, 2015 to 2023). A primary or metastatic malignant neoplasm involving the stomach. "In-keeping with this, MED30 was recently identified as an upregulated gene in stomach cancer connected with cancer proliferative properties and in development of cardiomyopathy in mice carrying a missense mutation in the first exon." (PMID 28603670, 2017). "Knockdown of MED30 inhibited the proliferations of all gastric cancer cells tested (SNU16, SNU216, SNU620, and SNU638) versus SCR by 18%, 68%, 98%, and 42%, respectively." (PMID 26110885, 2015). "We also examined the expression pattern of MED30 in gastric cancer cell lines by real-time PCR, and found it to be overexpressed in five of the gastric cancer cell lines tested (except SNU1) versus normal gastric tissues." (PMID 26110885, 2015). "In the present study, to reveal the functional importance of MED30 during gastric cancer progression, we examined its roles in proliferation, migration, invasion and tumorigenicity of gastric cancer cells." (PMID 26110885, 2015). "To examine roles of MED30 in gastric carcinogenesis, we examined the effects of MED30 knockdown or overexpression on the proliferation, migration, and invasion of the six gastric cancer cell lines (SNU1, SNUI16, SNU216, SNU620, SNU638, and NCI-N87 cells)." (PMID 26110885, 2015). "Although further studies are required to determine how MED30 triggers EMT, our results suggest that MED30 be considered a novel molecular target for the treatment of gastric cancer." (PMID 26110885, 2015). "To investigate roles played by MED30 in gastric cancer, we first examined the expression status of MED30 in the tumor tissues of 23 gastric cancer patients." (PMID 26110885, 2015). "To investigate the correlation between MED30 expression and clinical characteristics, we performed immunohistochemistry using 41 gastric cancer tissue samples." (PMID 26110885, 2015). "MED30 protein was found to be widely overexpressed in cancerous tissue regions, and was obviously overexpressed in invading gastric cancer cells and in metastatic cancer cells inside affected lymph nodes." (PMID 26110885, 2015). "It was found MED30 regulated the proliferation, migration, and invasion of gastric cancer cells and their in vivo tumorigenicity." (PMID 26110885, 2015). "Before the functional examination, we checked the expression pattern of MED30 in gastric cancer cells and tissues." (PMID 26110885, 2015). "In gastric cancer, overexpression of MED30 increases proliferation, migration, and invasion." (PMID 36271693, 2023). "Furthermore, we also found that MED30 was overexpressed in gastric cancer tissues and gastric cancer cell lines." (PMID 26110885, 2015). "Correlation between the expression of MED30 and clinical classification in the gastric cancer." (PMID 26110885, 2015). "Furthermore, MED30 overexpression induced a fibroblast-like morphology, which suggests MED30 triggers EMT in gastric cancer cells." (PMID 26110885, 2015). "In this study, we examined the functional roles of MED30 during gastric cancer progression." (PMID 26110885, 2015). "After ensuring knockdown and overexpression efficiency by quantitative real-time PCR and western blot analysis, we found that MED30 knockdown remarkably suppressed the proliferation, migration, and invasion of gastric cancer cells, and that MED30 overexpression had the opposite effects." (PMID 26110885, 2015). "In the present study, we examined the functional roles of MED30 during gastric cancer progression." (PMID 26110885, 2015). "It was found that MED30 was overexpressed in gastric cancer tissues and cell lines." (PMID 26110885, 2015). "Moreover, MED30 overexpression increased the proliferation, migration, and invasion of gastric cancer cells, whereas MED30 knockdown inhibited these effects." (PMID 26110885, 2015). "Summarizing, the present study supports the notion that MED30 acts as an oncogene during gastric carcinogenesis and suggests MED30 might regulate EMT in gastric cancer." (PMID 26110885, 2015).
glioblastoma (3 papers, 2022 to 2026). The most malignant astrocytic tumor (WHO grade IV). "One of the genes found in the CNA omic dataset is MED30, a core subunit in a group of mediator complex subunits that are mutated in various malignancies in glioblastoma (GBM), a malignant form of glial cell cancer." (PMID 35205681, 2022). "Functional studies in pancreatic ductal adenocarcinoma and glioblastoma demonstrate that MED30 is oncogenic and serves as a prognostic marker independent of MYC amplification." (PMID 42275218, 2026). "Using another cancer type as an example, MED30 knockdown reduces tumor growth particularly in MYC high-expressed glioblastoma (GBM) cell lines." (PMID 38766212, 2024).
pancreatic ductal adenocarcinoma (2 papers, 2024 to 2026). An infiltrating adenocarcinoma that arises from the epithelial cells of the pancreas. "In vivo studies in pancreatic ductal adenocarcinoma (PDAC) further validate the oncogenic potential of MED30, as its overexpression promotes tumor growth and can be attenuated by knockdown of MYC." (PMID 38766212, 2024).
atherosclerosis (1 paper, 2017). A disease characterized by the build-up of fatty material and calcium deposition in the arterial wall resulting in partial or complete occlusion of the arterial lumen. "Therefore, MED30 gene-related functions may play a role in mitigating the downstream effects of HIV in atherosclerosis and other cardiovascular complications." (PMID 29206233, 2017).
clear cell renal cell carcinoma (1 paper, 2023). "In clear cell renal cell carcinoma, the knockdown of MED30 results in a significant decrease in proliferation, migration, and invasion." (PMID 36271693, 2023).
Cornelia de Lange syndrome-4 (1 paper, 2021). "Recently, Mediator subunit 30 (MED30), a metazoan specific Mediator subunit, has been associated with Langer-Giedion syndrome (LGS) Type II and Cornelia de Lange syndrome-4 (CDLS4), characterized by several abnormalities including congenital heart defects." (PMID 34506481, 2021). "Recently, Mediator subunit 30 (MED30, also named TRAP25) has been associated with Langer-Giedion syndrome (LGS) Type II and Cornelia de Lange syndrome-4 (CDLS4), characterized by multiple congenital anomalies including heart defects." (PMID 34506481, 2021).
Kawasaki disease (1 paper, 2016). A rare inflammatory disease characterized by an acute febrile, systemic, self-limiting, medium-vessel vasculitis primarily affecting children. "MED30 was previously reported as a suggested association with Kawasaki disease in Han Chinese population." (PMID 27976721, 2016).
leprosy (1 paper, 2016). Leprosy is a chronic infectious disease affecting primarily the skin and peripheral nervous system. "We confirmed all the known leprosy susceptibility loci and identified four novel loci on 3p25.2 (SYN2), 7p14.3 (BBS9), 8p23.1 (CTSB) and 8q24.11 (MED30)." (PMID 27976721, 2016). "The SNP rs10100465 located nearby MED30 gene, which was down-regulated in the skin of leprosy patients." (PMID 27976721, 2016).
papillary renal cell carcinoma (1 paper, 2023). A rare subtype of renal cell carcinoma, arising from the renal tubular epithelium and showing a papillary growth pattern, which typically manifests with hematuria, flank pain, palpable abdominal mass or nonspecific symptoms, such as fatigue, weight loss or fever. "In addition, overexpression of MED30 in papillary renal cell carcinoma is significantly associated with poorer overall survival." (PMID 36271693, 2023).
cancer (8 papers, 2015 to 2026). A tumor composed of atypical neoplastic, often pleomorphic cells that invade other tissues. "Similar effects on cell cycle and cell viability have been observed in Med30 knockdown cancer cell lines." (PMID 34506481, 2021). "We next investigated the role of MED30 in the proliferation of cancer cells." (PMID 26110885, 2015). "However, the expressions and roles of MED30 have been poorly characterized in cancer." (PMID 26110885, 2015). "Overall, our study elucidates the critical role of MED30 overexpression in orchestrating oncogenic transcriptional programs and highlights its potential as a therapeutic target for MYC-amplified cancer." (PMID 38766212, 2024). "Here, we investigate the co-amplification of MED30 and MYC across diverse cancer types and its impact on oncogenic transcriptional programs." (PMID 38766212, 2024). "Best predicted cancer immunotherapy proteins with BC were RPS27, SUPT4H1, CLPSL2, POLR2K and RPL38, and the most altered ones were POLR2K, ASH2L, MED30, NSL1 and RPRD2." (PMID 32444848, 2020). "The integration sites at the two hotspots, chr1: 34,397,059 (CSMD2) and chr8:118,557,327 (MED30/EXT1), were not reported in previous HBV integration studies (except in this dataset as we previously reported), but overlapped with multiple fusion events from both cancer cell lines and TCGA." (PMID 35710421, 2022).
tumor (7 papers, 2010 to 2026). "The results showed MED30 knockdown significantly reduced tumor volumes and weights." (PMID 26110885, 2015). "Moreover, this study, for the first time, demonstrated MED30 and DEPDC6 as relapse-related genes which significantly associated with an increased risk of tumor relapse, including local recurrence, neck lymph node metastasis, and distant metastasis." (PMID 21853135, 2011). "The mechanism by which DEPDC6 and MED30 promote tumor relapse warrants further investigation." (PMID 21853135, 2011). "To examine the effect of MED30 on tumor growth, we subcutaneously injected SNU638 cells transfected with SCR or MED30 siRNA into SCID mice, and then monitored tumor growth for seven weeks." (PMID 26110885, 2015). "Besides frequent MYC MED30 co-amplification, MED30 overexpression alone is sufficient to enable MYC occupancy and activation of previously weak or unbound enhancers and promoters, driving tumor-promoting gene expression." (PMID 42275218, 2026). "The top 100 genes that correlated with NUDCD1 expression indicated 4 common members: FAM91A1, DCAF13, MED30 and DDX21, and their corresponding expression in different tumor types could be established." (PMID 37338527, 2023). "Immunohistochemistry (IHC) analysis of tumor biopsy samples confirmed a loss of CSMD2 and enhanced EXT1 expression in tumor and PVTT cells, whereas MED30 expression was unchanged (data not shown)." (PMID 31200735, 2019). "MED30 induced the expressions of EMT-related genes (N-cadherin; CDH2, P-cadherin; CDH3, twist related protein 1 and 2; TWIST1/2, vimentin; VIM), but inhibited the expression of E-cadherin (CDH1) a known tumor suppressor." (PMID 26110885, 2015).
infection (3 papers, 2017 to 2023). The state of being infected such as from the introduction of a foreign agent such as serum, vaccine, antigenic substance or organism. "Med30 and Med31 display unique phenotypes, in that they are required for host defense against three types of infections, including E. faecalis and A. fumigatus." (PMID 33746938, 2020). "Med30 RNAi flies are the only ones to be sensitive to C. glabrata whereas Med31 flies are susceptible to injected M. robertsii conidia but not in a natural infection paradigm." (PMID 33746938, 2020). "The occurrence of a macromolecular assembly (through proteins such as MED30 and NDUFB11) and cellular localization (through proteins such as FIS1) seems to occur as part of the 48-h post-infection pattern, thereby suggesting that the cells experience enormous energy expenditure." (PMID 38087340, 2023).
MED30 also shares sentences with these, for which no sentence is quoted: cardiomyopathy (2 papers); adenoma (1); HIV-1 infection (1); Langer-Giedion syndrome (1); metabolic disorders (1); metastatic cancer (1); Myocardial fibrosis (1); stomach cancer (1).